AR (androgen receptor)
Diseases named in the same sentence as AR in open-access papers (continued):
Sharing a sentence is not in itself a finding about the gene and the disease.
Hyperinsulinemia (6 papers, 2015 to 2025). An increased concentration of insulin in the blood. "In comparison, studies have shown that males carrying transcriptional variants of the Androgen Receptor (AR) gene with reduced activity are more susceptible to hyperinsulinemia." (PMID 41470893, 2025). "By reducing hyperinsulinemia, metformin can influence multiple other cancer pathways, including IGF (insulin growth factor) and PI3K-AKT/AR signalling, both of which are linked with PCa prognosis and castrate resistance." (PMID 29211393, 2018). "Androgens may also exert direct AR-dependent effects on adipocyte differentiation and function, and hyperinsulinemia and visceral obesity are reported in male mice lacking the AR in adipose tissue, although others found no similar phenotypes." (PMID 25550469, 2015).
ischemia (6 papers, 2014 to 2022). A hypoperfusion of the BLOOD through an organ or tissue caused by a PATHOLOGIC CONSTRICTION or obstruction of its BLOOD VESSELS, or an absence of BLOOD CIRCULATION. "Inhibition protects from ischemia through modulation of NMDA receptor subunit expression; knockout protects males but not females from effects of ischemia through a mechanism that involves the androgen receptor." (PMID 34680922, 2021). "Knockout of the TPRM2 protects male, but not female, mice from effects of ischemia, and interaction with the AR through PARP1 has been proposed as the mechanism." (PMID 26557979, 2015).
liver fibrosis (6 papers, 2019 to 2025). "Previous studies demonstrated that chronic HBV and HCV infection is male-dominant; HBV and HCV infection could enhance androgen receptor-mediated signaling that potentially triggers the carcinogenesis and progression of liver fibrosis." (PMID 36680166, 2022). "In addition, among all common targets for RGGs and liver fibrosis, ESR1, ESR2, AR, ACHE, CYP19A1, and AKR1B1 have a high degree of interaction with other targets and some active compounds." (PMID 35115923, 2021). "In addition, the use of adrenergic receptor (AR) blockers, such as nonselective α-AR and β-AR antagonists, inhibits the growth of HSC and reduce liver fibrosis." (PMID 31183386, 2019).
muscle atrophy (6 papers, 2016 to 2025). "Further investigation may shed light onto the pathogenetic processes occurring in mice that model a hypermorphic AR GOF, thereby providing a molecular link between muscle atrophy and disorders with amplification of AR function." (PMID 32019272, 2020).
ovarian dysfunction (6 papers, 2013 to 2023). The inability of the ovaries to function. "Notably, we have shown previously that GC-specific knockout of AR causes premature ovarian failure characterized by higher rate of atresia and fewer ovulated oocytes." (PMID 33784295, 2021). "Ovarian failure arising from inadequate androgen hormone levels and decreased androgen receptor function following aluminum exposure have also been documented." (PMID 36624872, 2023). "In AR knock out (ARKO) studies in rodents, global AR-null mice showed aberrant folliculogenesis with lower numbers of antral follicles and fewer oocytes after stimulation, they were sub-fertile and developed premature ovarian insufficiency." (PMID 33013703, 2020).
sarcomatoid carcinoma (6 papers, 2016 to 2025). A malignant epithelial neoplasm characterized by the presence of spindle cells and anaplastic morphologic features. "The expression of AR and CK8 but loss of E-cadherin suggests that the sarcomatoid carcinomas retain luminal epithelial cell properties and undergo EMT, providing a clear evidence of disease progression." (PMID 30677079, 2019). "This is consistent with the tumor phenotypes where adenocarcinomas typically express AR while sarcomatoid carcinomas lose the AR expression." (PMID 27036046, 2016). "Furthermore, immunohistological examination of serial subcutaneous tumor sections stained with AR showed that PLum-AD adenocarcinoma displayed strong homogenous nuclear labeling of AR compared to PLum-AI sarcomatoid carcinoma which showed a low expression for AR." (PMID 27036046, 2016). "Additionally, androgen receptor (AR) and prostate-specific antigen (PSA) are typically negative in sarcomatoid carcinoma." (PMID 39301540, 2024).
schizophrenia (6 papers, 2014 to 2024). A major psychotic disorder characterized by abnormalities in the perception or expression of reality. "Given the role of estrogen in the treatment of schizophrenia, we also examined sex hormone-related expression (AR, ESR1, ESR2, and PGR) in the brain." (PMID 38730231, 2024). "Testosterone is elevated in the cerebrospinal fluid of schizophrenia patients, and the androgen receptor is up-regulated in patients with bipolar disorder." (PMID 34211505, 2021). "Here, we did not observe any sex-specific or sex-specific schizophrenia DEGs for sex hormone expression (AR [androgen receptor], ESR1 [estrogen receptor 1], ESR2 [estrogen receptor 2], and PGR [progesterone receptor]) across the brain." (PMID 38730231, 2024).
spinal muscular atrophy (6 papers, 2023 to 2026). A motor neuron disease that affect the muscles, and characterized by muscle weakness and atrophy resulting from progressive degeneration and irreversible loss of the anterior horn cells in the spinal cord (i.e., lower motor neurons) and the brain stem nuclei. "In a mouse model of severe spinal muscular atrophy, murine skeletal muscle growth and fiber composition were regulated via the transcription factor STAT5a/b, linking growth hormone to the androgen receptor." (PMID 39309455, 2024). "Variants in AR have been found to cause spinal and bulbar muscular atrophy of Kennedy (OMIM#313200), an X-linked recessive form of spinal muscular atrophy, but none of the divergent allele lengths in the probands were longer than the described pathogenic length." (PMID 36701310, 2023).
spinocerebellar ataxias (6 papers, 2014 to 2024). "The microtubule-associated MID1 protein complex associates with AR mRNA via purine-rich trinucleotide repeats, expansions of which are known to correlate with ataxia and cancer." (PMID 24913494, 2014). "This study involved six genes (ATXN1, ATXN3, ATXN7, HTT, NOP56, and PPP2R2B), while a higher detection rate has been reported in a spinocerebellar ataxia cohort (4.4%, 22/498), which included five genes (ATXN2, ATXN3, NOP56, AR and HTT)." (PMID 38308084, 2024).
Testicular atrophy (6 papers, 2013 to 2024). Wasting (atrophy) of the testicle (the male gonad) manifested by a decrease in size and potentially by a loss of fertility. "The decrease in the number of Sertoli cells expressing AR may be the cause of delayed maturation, as well as testicular atrophy and a study performed in the cell culture conditions showed that amount of AR in Sertoli cells (as well as iRNA for AR) is dependent on FSH concentration." (PMID 34261436, 2021). "In conjunction with testicular atrophy, we observed a reduction in testes androgen receptor expression during the progression of cachexia." (PMID 24285707, 2013). "Furthermore, BOL treatment has been found to decrease the number of Sertoli AR cells, thereby explaining the observed maturing disturbances and testicular atrophy." (PMID 33126548, 2020).
thyroid tumor (6 papers, 2015 to 2023). A benign or malignant neoplasm affecting the thyroid gland. "The same study group also found a varying pattern of testosterone levels and AR status in the thyroid tissues of men and women, quite possibly hinting at the gender-specific incidence of thyroid tumors." (PMID 37190127, 2023). "Analysis of changes in function of thyroid tumor cells, using an in-vitro gain of AR function model, showed that overexpression of AR in BCPAP and TPC-1 cells reduced cell migration." (PMID 32365531, 2020). "The distinct patterns of testosterone and androgen receptor expression patterns observed in the thyroid tissues of men and women could contribute to the gender-specific incidence of thyroid tumors." (PMID 37924384, 2023). "Furthermore, our data indicates that AR is significantly downregulated in both male and female thyroid tumors compared to normal tissues." (PMID 34422798, 2021). "For example, a study of 100 benign and 105 malignant thyroid tumors using a panel of 57 molecular markers found an association of tumor pathology with the expression of a subset of markers including cytokeratin 19 (CK19), LGALS3, HBME-1, VEGF, AR, p16, and AURKA." (PMID 25887408, 2015).
Apocrine breast carcinoma (5 papers, 2014 to 2024). "In fact, LAR subtype or apocrine breast carcinoma is characterized by the expression of AR oncogene that contributes to breast tumorigenesis." (PMID 30093977, 2018). "Given that AR and HMGCS2 are both overexpressed in IAC, the use of the dual therapy targeting two parallel AR and HMGCS2 pathways may provide an additional benefit for therapeutic attack of breast apocrine carcinoma." (PMID 25389781, 2014).
cholangiocarcinoma (5 papers, 2020 to 2025). A carcinoma that arises from the intrahepatic biliary tree (intrahepatic cholangiocarcinoma) or from the junction, or adjacent to the junction, of the right and left hepatic ducts (hilar cholangiocarcinoma). "We noted several genetic alterations in AR across multiple tumor types with cholangiocarcinoma demonstrating the highest frequency of structural variants out of the 32 tumor types evaluated." (PMID 39300603, 2024). "While within individual tumor types there was a broad range of expression, cholangiocarcinoma demonstrated AR expression." (PMID 39300603, 2024).
Cirrhosis (5 papers, 2017 to 2025). A chronic disorder of the liver in which liver tissue becomes scarred and is partially replaced by regenerative nodules and fibrotic tissue resulting in loss of liver function. "AR was elevated in the rat cirrhosis model by qRT-PCR experiments." (PMID 35330838, 2022). "AR mRNA ranked at the top 3% and 7% of the significantly altered genes in HCV-positive HCC and HCV-positive cirrhosis respectively, in comparison with the HCV-negative normal subjects (p < 0.001)." (PMID 28978011, 2017).
cognitive disorder (5 papers, 2019 to 2025). A disease affects cognitive processes. "Motif analyses of the promoters for these cognition-related genes revealed a common binding motif for the androgen receptor, suggesting that the androgen receptor may play an important role in sex-related differences in neonatal susceptibility to cognitive deficits." (PMID 31333645, 2019). "Taken together, this evidence supports androgens and AR influencing cognitive impairments in ALS more strongly than providing neurotrophic support to UMNs." (PMID 35273564, 2022). "The AR antagonist darolutamide demonstrated a comparable incidence of cognitive disorder in clinical trials to that of ADT alone." (PMID 31844181, 2020). "Darolutamide’s low blood–brain barrier penetration may reduce the incidence of fatigue and cognitive impairment compared with other androgen receptor inhibitors." (PMID 41415573, 2025).
congenital adrenal hyperplasia (5 papers, 2016 to 2025). Congenital adrenal hyperplasia (CAH) is an inherited endocrine disorder caused by a steroidogenic enzyme deficiency that is characterized by adrenal insufficiency and variable degrees of hyper or hypo androgyny manifestations, depending of the type and the severity of the disease. "Examples include the erythropoietin receptor (EPOR), the androgen receptor (AR) [complete androgen insensitivity (CAIS)], and some hormonal excesses and deficiencies (virilizing adrenal hyperplasia and genetic growth hormone deficiency, and likely myostatin deficiency)." (PMID 29075233, 2017).
developmental delay (5 papers, 2018 to 2025). "The AR variant was also detected in his younger sibling with ambiguous genitalia and normal development whereas the youngest sibling with ambiguous genitalia and developmental delay was not tested." (PMID 33942428, 2021).
diffuse large B-cell lymphoma (5 papers, 2015 to 2026). "In line, recent reports suggested potential therapeutic or prognostic applications to targeting the AR axis in other lymphoid malignancies such as mantle cell lymphoma and diffuse large B cell lymphoma." (PMID 29781039, 2018).
disorders of sex development (5 papers, 2013 to 2026). "The objective of the study was to clarify this discrepancy by in vitro determination of AR transcriptional activity in individuals with disorders of sex development (DSD) and male controls." (PMID 27583472, 2016).
fibrosarcoma (5 papers, 2013 to 2024). A malignant mesenchymal fibroblastic neoplasm affecting the soft tissue and bone. "Our findings subsequently showed that 10 nM androgens significantly enhance extra-nuclear association and co-localization of AR with the full-lenght FlnA in fibroblasts and fibrosarcoma-derived cells." (PMID 33500395, 2021). "KIF20A promotes the progression of castration-resistant prostate cancer by activating androgen receptor signaling and promotes the progression of fibrosarcoma via the PI3K-Akt signaling pathway." (PMID 39902297, 2024). "At 10 nM concentration, the stapled peptide specifically disrupts the androgen-induced AR/FlnA complex assembly and motility in mouse and HNFs, as well as human fibrosarcoma-derived HT1080 cells." (PMID 33500395, 2021). "Our study shows that AR inhibition by Casodex results in significant antitumor activity against fibrosarcoma in vitro and in vivo." (PMID 24130806, 2013). "Findings: We report that the pure anti-androgen Casodex inhibits the growth of HT1080 cell xenografts in immune-depressed mice, revealing a novel role of AR in fibrosarcoma progression." (PMID 24130806, 2013). "By competing for AR/Src Association, the S1 peptide prevents the EGF mitogenic signaling in fibrosarcoma cells." (PMID 24130806, 2013). "Therefore, AR represents a new potential therapeutic target in human fibrosarcoma, as supported by Casodex inhibition of HT1080 cell xenografts." (PMID 24130806, 2013). "To date, this is the first evidence that targeting AR inhibits human fibrosarcoma cell growth." (PMID 24130806, 2013). "The non-genomic role of AR and Src is further supported by studies in a human fibrosarcoma cell line which expresses AR." (PMID 30416486, 2018).
germ cell tumor (5 papers, 2014 to 2026). A benign or malignant, gonadal or extragonadal neoplasm that originates from germ cells. "Silencing of androgen receptor (AR)-meditated androgen signaling is thought to be associated with the development of testicular germ cell tumors (TGCTs)." (PMID 27144435, 2016). "However, the role of androgen/AR signaling in testicular germ-cell tumors (TGCTs) remains unclear." (PMID 27144435, 2016). "The X chromosome is methylated by X-inactive specific transcript (XIST) in differentiated germ cell tumors but not in undifferentiated germ cell tumors, as shown in the case of the androgen receptor gene." (PMID 25153150, 2014). "The AR-mediated androgen signals cross-talk with proteins encoded by the Y chromosome (i.e. TSPY), and co-expression of TSPY and AR occurs in testicular germ cell tumors and model cell lines, but not in normal testicular cells." (PMID 24922532, 2014).
head and neck squamous cell carcinoma (5 papers, 2014 to 2023). A squamous cell carcinoma that arises from any of the following anatomic sites: lip and oral cavity, nasal cavity, paranasal sinuses, pharynx, larynx, and salivary glands. "AR is considered a favorable prognostic marker in head and neck squamous cell carcinoma (HNSCC), while other authors have reported adverse survival in salivary gland tumors." (PMID 35544472, 2022).
laryngeal squamous cell carcinoma (5 papers, 2015 to 2025). A squamous cell carcinoma that arises from the larynx. "AR expression varies in HNSCC at different sites; for example, the AR mRNA level was upregulated in laryngeal squamous cell carcinoma." (PMID 41228208, 2025).
Leydig cell tumor (5 papers, 2007 to 2024). A sex cord-stromal tumor occurring in the testis and rarely in the ovary. "The incidence of Leydig cell tumors in men who have a defective androgen receptor that makes them insensitive to androgens is considerably higher than for men without this syndrome (2.3% vs. ∼ 0.00004%)." (PMID 17805427, 2007). "We compared these data with those of 2 situations of pathology linked to androgens: 1/premature secretion of testosterone: 4 cases of Leydig cell tumor (LCT) in childhood; and 2 /defect of androgen receptors (AR): 4 cases of complete form of insensitivity to androgen syndrome (CAIS)." (PMID 34906089, 2021).
liposarcoma (5 papers, 2012 to 2022). A usually painless malignant tumor that arises from adipose tissue. "Recently, overexpression of the estrogen receptor and androgen receptor in well-differentiated and dedifferentiated liposarcoma was reported." (PMID 27247814, 2016). "AR overexpression was seen in 18.3–54.2% of myxoid chondrosarcoma, DSRCT, pleomorphic and well-differentiated liposarcoma, ESS and LMS." (PMID 25906748, 2015).
lupus (5 papers, 2014 to 2023). "Conversely, females with lupus who had shorter AR exon 1 CAG repeats (which are associated with relatively amplified hormonal action) were found to have greater disease activity and more robust humoral autoimmune responses." (PMID 24711544, 2014). "Finally, male lupus patients with reduced AR signaling produce higher quantities of IgG autoantibodies, while female lupus patients with the same polymorphism exhibited reduced disease." (PMID 29755457, 2018). "We analyzed each individual subject's X chromosomal methylation at CpG islands in close proximity to exon 1 of the androgen receptor gene to assess whether preferential expression of AR alleles of greater or lesser length might be more prevalent in the lupus subjects." (PMID 24711544, 2014). "We sought to determine whether differences in androgen sensitivity conferred by variation in the exon 1 CAG repeat region of the androgen receptor (AR) gene were associated with differences in the clinical or humoral immune manifestations of lupus in a cohort of female subjects." (PMID 24711544, 2014). "Further, treatment with both testosterone and the endogenous AR agonist dihydrotestosterone ameliorates experimental lupus and arthritis, supporting a protective effect of AR activation." (PMID 29802242, 2018). "Our prior studies in men with lupus supported the formulation that attenuated androgen signaling through long AR CAG repeats resulted in increased manifestations of autoimmune phenomena." (PMID 24711544, 2014). "We found a significant inverse correlation between the level of expression of antinuclear antibodies and the weighted mean AR CAG repeat length in our cohort of lupus subjects (r2 =0.4730; P=0.0003)." (PMID 24711544, 2014). "To assess whether AR CAG repeat lengths differed between healthy individuals and subjects with lupus, we genotyped 25 healthy female volunteers and 39 women with a diagnosis of lupus who are subjects in a registry at the Milton S Hershey Medical Center." (PMID 24711544, 2014). "Importantly, while BAFF inhibition may be protective in experimental lupus models, the importance of BAFF regulation for the beneficial effects of testosterone/AR agonist in experimental disease models remains unclear." (PMID 29802242, 2018). "Our subjects exhibited normal distribution of their AR allele CAG repeat lengths and their enrollment in the Hershey Medical Center lupus registry was not biased for any particular manifestation of disease, for severity of manifestations, or for specific therapy." (PMID 24711544, 2014).